CCL17 (C-C motif chemokine ligand 17)
Diseases named in the same sentence as CCL17 in open-access papers (continued):
Sharing a sentence is not in itself a finding about the gene and the disease.
pulmonary fibrosis (continued). "Metformin treatment also reduced BALF levels of CCL17 and CCL2, cytokines we previously reported as being upregulated in AT2I73T cells and increased in the SftpcI73T mouse model of lung fibrosis." (PMID 40591409, 2025). "Elevated CCL17 levels in IPF patients and mice with bleomycin-induced pulmonary fibrosis (PF) indicate that the antibody-mediated CCL17 blockade protects against fibrosis." (PMID 39768150, 2024). "For instance, CCL22 and CCL17, secretd by M2 macrophages, can recruit CCR4+CD4+ T helper 2 cells, thereby contributing to the pathophysiology of pulmonary fibrosis." (PMID 38789926, 2024). "In a rat model of radiation pneumonitis/pulmonary fibrosis, CCL22 and CCL17 were upregulated in irradiated lung tissues." (PMID 35365161, 2022). "In the present study, the BALF levels of CCL17 also correlated with BALF neutrophils, supporting the relation between CCL17 and pathogenesis of pulmonary fibrosis." (PMID 31369605, 2019). "Previous reports suggested that CCL17 and the ligand CCR4 contribute to development of pulmonary fibrosis by inducing infiltration of alveolar macrophages and Th2 cells in a bleomycin mouse model." (PMID 31369605, 2019). "The TARC (CCL17)/IP-10 (CXCL10) ratio was described as a marker for fibrogenesis in the lung in patient with usual interstitial pneumonia and subsequent idiopathic pulmonary fibrosis." (PMID 26807786, 2016). "We examined the expression of CCR4, a specific receptor for CCL22 and CCL17, in bronchoalveolar lavage (BAL) fluid cells, as well as the levels of CCL22 and CCL17, to elucidate their pathophysiological roles in pulmonary fibrosis." (PMID 19715610, 2009). "The precise involvement of several other cytokines, including IL-1b, IL-17, IL-10, thymus and activation-regulated chemokine (CCL17), and GM-CSF, in the process of pulmonary fibrosis is still debatable or mechanistically unknown." (PMID 40136649, 2025). "The study showed that CCL17 is a pro-fibrotic mediator of lung fibroblasts, suggesting that CCL17 or CCR4 inhibition may serve as an effective strategy to suppress lung fibroblast activation and attenuate pulmonary fibrosis progression." (PMID 37681924, 2023). "Further experiments showed that the CCR4 ligand CCL17/TARC plays a role in CCR4-dependent M1 activation leading to iNOS induction and oxidative injury, thereby affecting the development of bleomycin-induced pulmonary fibrosis." (PMID 30245686, 2018). "In the next step we analysed the TARC (CCL17)/IP-10 (CXCL10) ratio in our patient cohort as well as in cell culture, because a study by Kishi and colleagues revealed an elevated TARC (CCL17)/IP-10 (CXCL10) ratio in patients suffering from lung fibrosis." (PMID 26807786, 2016). "Thus, CCL22 and CCL17 are released by alveolar macrophages and may act on CCR4+ type-2 T helper cells and alveolar macrophages to promote pulmonary fibrosis." (PMID 35365161, 2022). "Then, drawing from previous evidence that Th2-predominant immune response may play an important role in the development of lung fibrosis in chronic HP, we also analyzed serum levels of CXCL9 (Th1 chemokine), CCL17 (Th2 chemokine), and Krebs von den Lungen 6 (KL-6)." (PMID 31369605, 2019). "In addition, as the combination of CCL17 and total POSTN showed excellent performance for predicting non-IPF-ILD progression in the discovery cohort, developing a combination of multiple biomarkers is expected to more accurately determine the complex pathogenesis of pulmonary fibrosis." (PMID 40269953, 2025).
eosinophilia (26 papers, 2006 to 2026). "Interestingly, in our study, CCL17/TARC was associated with blood eosinophilia only in patients with N-ERD." (PMID 41573581, 2025). "Basophil depletion during sensitization reduces lung eosinophilia and CCL17/CCL24 level, while additional basophil absence during challenge is required to also impair Il4/Il13 expression." (PMID 41074677, 2026). "In challenged lungs, reduced inflammation and eosinophilia were accompanied by lower levels of chemokines CCL17 and CCL24, which attract Th2 cells and eosinophils, respectively." (PMID 41074677, 2026). "The top proteins with the largest log2 fold change in this group included IL-19, STAT5B, CCL17, S100A12, and CCL22—inflammatory mediators known to be associated with AD inflammation and eosinophilia." (PMID 41357518, 2025). "IL-25 induces the chemokines necessary for eosinophilia and the recruitment of Th2 cells like eotaxin, thymus activation regulated chemokine (TARC)/CCL17, and macrophage-derived chemokine (MDC)." (PMID 39728140, 2024). "The association of CCL17 and eosinophilia with S. mansoni infection was not unexpected, since these mediators are markers of a type-2 immune response, which is frequently reported in helminth-infected individuals." (PMID 33777015, 2021). "Besides, our synbiotic, TP, and LGG strongly down-regulated eosinophilia, IL-5, CCL17, IL-13." (PMID 32582180, 2020). "IL-25 induces the expression of various chemokines, such as eotaxin, TARC (CCL17, thymus and activation-regulated chemokine) and MDC (macrophage-derived chemokine), which are necessary for the recruitment of eosinophilia and Th2 cells." (PMID 33923629, 2021). "Similar to CCR4 antibodies, specialized antibodies against TARC/CCL17 and CCL22 can reduce ovalbumin (OVA)-induced airway eosinophilia and hypersensitivity reactions in asthmatic mice." (PMID 33265990, 2020). "It has been demonstrated that proteins related to eosinophilia, first of all eoxtaxin-3, and to Th2 immune response in general, particularly IgG4 and CCL17/TARC, were elevated in active EGPA." (PMID 31244756, 2019). "The mRNA expression of CCL17 and CLEC10A correlated significantly with the degree of eosinophilia (each P < .01)." (PMID 24612750, 2014). "In our study CCL-17, CCL-27 and IL-18 serum levels correlated positively with total IgE in Group 2, and eosinophilia correlated positively with CCL-27." (PMID 19639049, 2009). "Macrophages in asthmatics’ sputum exhibited significantly upregulated CCL17 mRNA expression, which highly correlated with sputum eosinophilia, but other M2 biomarkers were not differentially expressed in asthmatic individuals." (PMID 35743888, 2022). "In line with this, in a model of schistosome egg induced pulmonary granulomatous inflammation, depletion of known eosinophil and Th2 cell chemokines CCL17 and CCL22, which can be produced by DCs, led to altered granuloma structure, including a dramatic reduction in eosinophilia." (PMID 35958580, 2022). "In the study population, S. mansoni-infected individuals showed a higher rate of eosinophilia, higher serum concentrations of CCL3 and CCL17, and a higher frequency of IL-17 responders in comparison with all the other groups of non-Schistosoma-infected individuals." (PMID 33777015, 2021). "Significant correlations between CCL-17 and the severity of various diseases were published, highlighting its usage in allergic conditions, but no data exist on non-allergic asthma with predominant eosinophilia." (PMID 31438916, 2019). "In our study, the cytokine profile of peptide 23-immunized mice depicting elevated CCL17, CCL22, and IL-18 might have contributed to the antiviral responses rather than the induction of lung inflammation, in which no significant eosinophilia was observed." (PMID 21980478, 2011).
Hodgkins lymphoma (24 papers, 2012 to 2024). A heterogeneous group of malignant lymphoid neoplasms of B-cell origin characterized histologically by the presence of Hodgkin and Reed-Sternberg (HRS) cells in the vast majority of cases. "The strongest association was observed for CCL17/TARC, a biomarker elevated in Hodgkin lymphoma patients." (PMID 34771561, 2021). "In lymphomas, CCL17 was specifically expressed in classical Hodgkin’s lymphoma, whereas CCL22 was expressed in nodular lymphocyte-predominant Hodgkin’s lymphoma and B-cell non-Hodgkin’s lymphoma." (PMID 38077392, 2023). "This receptor binds to Chemokine (C-C Motif) Ligand 17 (CCL17) secreted by Hodgkin lymphoma cells which in turn improves CAR-T cell trafficking into tumor site." (PMID 36389658, 2022). "Our findings show an increase in cHL tissue predominantly in patients with nodular sclerosis and a significant increase in plasma, congruent with previous studies of CCL17 in cHL, supporting the central role of CCL17 in the pathophysiology of cHL." (PMID 35008176, 2021). "CCL17 is a well-known biomarker in cHL and elevated in serum of pretreated cHL patients, with predominance in patients with nodular sclerosis." (PMID 35008176, 2021). "CCL17 NPX levels in cHL tissues were higher in cHL nodular sclerosis subtype cases (p = 0.029)." (PMID 35008176, 2021). "Since the growth and metastasis of malignant tumor should be attributed to abnormal angiogenesis and elevated expression of CCL17 was found in Hodgkin's disease, we speculated that CCL17 was essential for regulation of angiogenesis." (PMID 25401103, 2014). "Unlike the expression pattern we observed in Hodgkin lymphomas, where CCL17/22 expression was strongly linked to EBV-positivity, the NPCs showed chemokine expression that appeared to be a combination of tumor cell-intrinsic and expression by tumor-infiltrating EBV- cells." (PMID 35025968, 2022). "CCL17/TARC is another biomarker with the potential to facilitate primary care triage and chemotherapy monitoring strategies for classic Hodgkin lymphoma (cHL)." (PMID 36772521, 2023). "Meanwhile, high levels of CCL17 and CCL22 were detected in a variety of tumors, such as lung cancer, gastric cancer, B-cell non-Hodgkin’s lymphoma, Hodgkin’s lymphoma, and peripheral T-cell lymphoma." (PMID 38077392, 2023). "Patient samples from lymphoblastic (Hodgkin lymphoma) and epithelial (nasopharyngeal carcinoma; NPC) EBV+ tumors revealed CCL17 and CCL22 expression of both tumor cell-intrinsic and -extrinsic origin, depending on tumor type." (PMID 35025968, 2022). "Under dual PI3Kδ/γ inhibition, a decrease of macrophage-attracting chemokines (i.e., CSF-1, CCL5, TARC/CCL17) is seen and leads to a significant reduction of F4/80+ TAMs in Hodgkin lymphoma xenografts." (PMID 31454887, 2019). "Thus, they hypothesized that CCL17 could act as the biomarkers for Hodgkin's disease." (PMID 25401103, 2014). "Moreover, the activation of CC-chemokine ligand 17 (CCL17) and CCL22, secreted by Reed–Sternberg cells of Hodgkin lymphoma (HL), activated their receptor CC-chemokine receptor 4 (CCR4) expressed T helper cells and Tregs." (PMID 39134804, 2024). "Previous study also showed that the chemotherapy-sensitive Hodgkin lymphoma patients had frequent gains of 16q13, a chromosomal region known to house genes that regulate T-cells trafficking or NF-ĸB activation (CX3CL1, CCL22, CCL17, DOK4, and IL10)." (PMID 37153002, 2023). "Moreover, it has been noted that two CCR4 ligands -CCL17 and CCL22-, are overexpressed in lymphoid malignancies such as Hodgkin’s lymphoma (HL), and in many other types of human cancers including ovarian, breast, esophageal and gastric cancers." (PMID 35211124, 2022).
atherosclerosis (23 papers, 2012 to 2025). A disease characterized by the build-up of fatty material and calcium deposition in the arterial wall resulting in partial or complete occlusion of the arterial lumen. "Our previous studies demonstrated that serum CCL17 levels are associated with coronary artery disease and atherosclerosis severity, independently of traditional cardiovascular risk factors." (PMID 35687056, 2022). "In atherosclerosis-prone ApoE−/− mice fed a high fat diet for 4 weeks, CCL17 deficiency attenuated atherosclerosis in a Treg-dependent manner." (PMID 33503867, 2021). "The reduction of atherosclerosis in Ccl17-deficient atherosclerosis-prone mice was shown to be dependent on Treg cells, and CCL17 expression by DCs limited the expansion of that cell subset." (PMID 29099057, 2017). "In ApoE−/− mice, Ccl17 deficiency entailed a reduction of atherosclerosis, which was dependent on T-regulatory cells." (PMID 27491335, 2016). "Deficiency in Ccl17 in ApoE−/− mice resulted in reduced atherosclerosis that was supported by immunoregulatory functions of Treg cells." (PMID 24741577, 2014). "Moreover, we and other studies have demonstrated that chemokine CCL17, an important regulator of atherosclerosis, is positively associated with coronary artery disease, independent of traditional cardiovascular risk factors." (PMID 35687056, 2022). "A limitation of the present study is that only the ApoE−/− mouse model was employed to investigate the role of SENP3-mediated DeSUMOylation of CCL17 in atherosclerosis." (PMID 41266856, 2025). "An interesting study found that CCL17 derived from dendritic cells accumulated in pathological tissues in AS mice, and accelerated the process of atherosclerosis by regulating the steady state of Tregs." (PMID 41266856, 2025). "Our study also found that SENP3 exacerbates atherosclerosis through a novel mechanism involving the deSUMOylation of CCL17." (PMID 41266856, 2025). "CCL17 has been previously shown to drive atherosclerosis through suppression of regulatory T-cell functions and Cx3cl1 is an established as a pro-atherogenic chemokine." (PMID 40893367, 2025). "In animal experiments, KO of CCL17 genes delayed progression of atherosclerosis and attenuated ischemia-reperfusion injury." (PMID 37940228, 2023). "CCL17 is a chemokine that is selectively expressed in human macrophages and plays a pivotal role in atherosclerosis by promotion of leukocyte infiltration into endothelial cells." (PMID 37940228, 2023). "In further exploration of the subsets of DCs, it was found that CD11b+DC and CCL17+DC subsets have the effect of promoting atherosclerosis, and further exploration under more experimental conditions will provide multi-dimensional evidence." (PMID 35062863, 2022). "Since it has been demonstrated that the enhanced T cell number and activities within atherosclerotic lesions were associated with an enhanced atherosclerotic plaque growth, these data suggested that CCL17+DCs promote atherosclerosis." (PMID 32849502, 2020). "CCL17 is present in advanced human and mouse atherosclerosis and CCL17 and DCs accumulate in atherosclerotic lesions." (PMID 27491335, 2016). "CCL17 is a chemokine expressed by dendritic cells (DCs) that has been reported to promote atherosclerosis in a mechanism conferred by T cells." (PMID 27491335, 2016). "This review focuses on important findings gathered in these studies and dissects the multifaceted contribution of CCL17-expressing DCs and pDCs to the pathogenesis of atherosclerosis." (PMID 24818041, 2014). "Thus, we identified a novel role for the CCL17/CCL22–CCR4 axes in controlling early atherosclerosis via favorable modulation of the Th1 cell/Treg balance." (PMID 40608058, 2025). "One previous study on atherosclerosis in mice may relate to CCR4‐expressing Tregs; it demonstrated that dendritic cell‐derived CCL17 drove atherosclerosis by restricting T regulatory cell homeostasis." (PMID 37927302, 2023).
atherosclerosis (continued). "Additionally, dendritic cell-derived CCL17 was shown to drive development of atherosclerosis in a mouse model." (PMID 31222168, 2019). "We could thus reveal that CCL17 characterizes a DC-subset that is of paramount importance in the initiation and progression of atherosclerosis." (PMID 24818041, 2014). "Depletion of CCL17 has been shown to induce Tregs and inhibit atherosclerosis and might also show benefits in Ang II-induced vascular stiffening." (PMID 25258681, 2014). "For example, the dendritic cell-derived CCL17 could be identified as a catalyzer for atherosclerosis due to interference of Treg homeostasis in mice." (PMID 22807925, 2012). "Recently, dendritic cell-derived CCL17 has been found to be critical in atherosclerosis." (PMID 22807925, 2012). "CCL17 is involved in the induction or enhancement of a broad spectrum of immune reactions, ranging from contact hypersensitivity responses and allograft rejection to inflammatory bowel disease and various inflammatory diseases, such as atopic dermatitis and atherosclerosis." (PMID 29099057, 2017). "Among all these subsets, some exert protective functions in atherosclerosis development, for instance, CD103+ classical DCs; other subsets such as chemokine ligand CC family (CCL17)-expressing CD11b+ DCs restrain Treg responses and drive atherosclerosis." (PMID 30984201, 2019). "It has been found that AD patients have increased levels of markers of atherosclerosis including fractalkine/CX3CL1, CCL8, M-CSF, and HGF, as well as increased levels of mediators of atherosclerosis such as E-selectin or PI3/elafin, CCL17, and IL-16, which are proportional to SCORAD." (PMID 34551806, 2021). "While we could confirm the presence of numerous CD11c+ DCs in atherosclerosis-prone regions of naive mice, these did not express CCL17 under physiological conditions." (PMID 24818041, 2014). "Unlike acute myocardial infarction, where CCL17/CCL22 competition occurs transiently during acute inflammation, our study reveals that this chemokine interplay also exists in atherosclerosis, suggesting a chronic and persistent regulatory mechanism in immune cell recruitment and plaque progression." (PMID 41266856, 2025).
dermatitis (22 papers, 2012 to 2025). An inflammatory process affecting the skin. "Dupilumab treatment significantly improved dermatitis and decreased total serum IgE and serum CCL17 (also known as TARC) levels in patients with AD, although some patients were low responders." (PMID 34909707, 2021). "IL-31 may enhance skin inflammation through the induction of several chemokine genes such as CCL17, CCL22 and CCL1 in human keratinocytes which subsequently leads to the recruitment of T-cells, and in turn may become new sources of IL-31." (PMID 22853438, 2012). "At the same time, systemic administration of anti-CCR4 ligand (CCL17 and CCL22) and CCR10 ligand (CCL27) comprehensive antibody can significantly inhibit T cell migration and skin inflammation." (PMID 40040698, 2025). "The CCR4 specific ligands, CCL17 and CCL22, induce persistent immune cell accumulation at skin inflammation sites." (PMID 34451592, 2021). "Proinflammatory cytokines and chemokines secreted by keratinocytes, such as TNF-α, IFN-γ, IL-1β, IL-6, IL-8, TARC (CCL17), MDC (CCL22), and RANTES, play a very important role in dermatitis." (PMID 34361003, 2021). "Stimulation with TNF-α/IFN-γ induces the production of pruritic cytokines and chemotactic chemokines in keratinocytes such as TSLP, IL-31, CCL17/TARC, and CCL22/MDC, further expanding skin inflammation with the recruitment of major T cell lineage, Th2 cells, resulting in epidermal damage." (PMID 37958804, 2023). "Therefore, CCL17 and CCR4 are important in lymphocyte-selective skin homing, and both are synergistically involved in the interaction between TEM homing to the skin and the site of skin inflammation and vascular endothelium." (PMID 40040698, 2025).